NOTCH1 (notch receptor 1)
Diseases named in the same sentence as NOTCH1 in open-access papers (continued):
Sharing a sentence is not in itself a finding about the gene and the disease.
glioma (continued). "As the CXCR4 positive glioma initiating cells co-expressed with Notch1 usually dispersed in the periphery of the tumorsphere, we put forward the hypothesis that CXCR4 might exert a crucial role in the Notch1 signaling mediated stem maintenance and migration of GICs." (PMID 31382985, 2019). "Moreover, it was demonstrated in vivo that si-circNFIX could suppress glioma growth by regulating miR-34a-5p and NOTCH1." (PMID 30072869, 2018). "In addition, Notch1 was upregulated in glioma cell lines, especially U87 and LN229." (PMID 30170559, 2018). "This suggests that the miR-139-5p/Notch1/EMT pathway could be a novel target for glioma therapy." (PMID 30170559, 2018). "However, little is known about the Notch1 interaction with EMT in glioma." (PMID 30170559, 2018). "However, the role of Notch1 in glioma EMT and associated microRNAs (miRNAs) with the Notch pathway remain controversial." (PMID 30170559, 2018). "However, little is known regarding Notch1 interactions with EMT in glioma." (PMID 30170559, 2018). "Therefore, Notch1 and its ligands may present novel therapeutic targets in the treatment of gliomas." (PMID 28950865, 2017). "Importantly, IDH mutated, 1p/19q codeleted gliomas were characterized by mutations in CIC, FUBP1, NOTCH1, and TERT promoter, suggesting these mutations could serve as oligodendroglial lineage markers." (PMID 27556304, 2016). "It indicated that suppress the expression of Notch-1 may induce autophagy in glioma." (PMID 26824182, 2016). "Similarly, the expression pattern of Notch-1 was also consistent with miR-92a-3p in glioma cells, which indicated that miR-92a-3p may regulate different targets in glioma cells and GSCs." (PMID 27801803, 2016). "Besides Notch3, Notch1 and Notch2 also protected glioma stem-like cells against radiation." (PMID 26273424, 2015). "Recent studies indicate that a deregulated miR-146a expression could contribute to glioma development through the targeting of NOTCH1, a cell signaling pathway playing a key role in the mechanism of neural stem cell development and maintenance in the adult life." (PMID 22453030, 2012). "Taken together, the PDGF‐D/NF‐κB/NOTCH1 axis regulates the migration, invasion, and EMT of glioma cells." (PMID 40530904, 2025). "Concurrently, γ-secretase inhibitor MK-0752 downregulates Notch1/Hes1 signaling, reducing AKT/mTOR phosphorylation and CXCR4 expression, thereby attenuating glioma stem cell aggressiveness." (PMID 40755759, 2025). "Key examples of oncogenic circRNAs are circNFIX (glioma) and circ‐ASH2L (pancreatic cancer), which drive tumor progression by sponging miR‐34a‐5p, elevating NOTCH 1 expression, and activating downstream effectors." (PMID 40761890, 2025). "Overall, NOTCH1 and SOX2, key regulators of EMT, are most frequently altered in both HGG and LGG, indicating their universal role across different glioma tumors." (PMID 40679044, 2025). "Notch1 can activate the AKT pathway, thereby enhancing the signaling of β-catenin and NF-κB to promote glioma cell migration and invasion, and the CXCL1/CXCR4 system can also enhance the migration and invasion capacity of GICs." (PMID 38672496, 2024). "The results were basically consistent with the previous transcriptome sequencing analysis and real time qPCR analysis results, substantiating the positive correlation between Notch1 gene and BRD4 protein in glioma." (PMID 39544152, 2024). "We therefore conclude that ARV‐825 can degrade BRD4 protein to downregulate the transcription of the Notch1 gene, reversing TMZ resistance in gliomas." (PMID 39544152, 2024). "More recently, a detailed analysis has revealed that in TRPM7-mediated Notch1 signaling, the expression of CD133 and ALDH1 are crucial in glioma cell proliferation and glioma stem cell stemness." (PMID 38255793, 2024). "HCMV infection also promotes the proliferation of U251 glioma cells by regulating the ATF5 signaling pathway to upregulate the expression of NICD and Notch1." (PMID 39205316, 2024).
glioma (continued). "Furthermore, the role of DLX6-AS1 has been reported as tumour-promoting in pancreatic cancer, non-small-cell lung cancer, and glioma through inhibiting miR-181b, miR-144, and miR-197-5p, respectively, yet their association with the Notch1 signalling pathway has not been investigated in detail." (PMID 37628760, 2023). "Overexpression of miR-499a leads to the inhibition of glioma cell proliferation and inhibition of the MAPK signaling pathway by reducing NOTCH1 to promote cell apoptosis." (PMID 37096442, 2023). "While the expression of NOTCH1 and its ligands affect glioma proliferation, the role of NOTCH signaling in glioma development appears context dependent and is incompletely understood." (PMID 35896929, 2023). "The miR-30c inhibitor enhanced the Notch1, NICD, HES1 and HEY1 proteins in A172 and U251 glioma cells, and shRNA-Notch1 weakened this enhancement." (PMID 36180477, 2022). "Vey similar tumor-suppressing activities of miR-139 on NOTCH1 levels, tumor cell growth, EMT and metastasis have been described in a mouse model for glioma." (PMID 35269391, 2022). "The Notch1 gene is reported to be significantly higher in the glioma stem cells and in the neurosphere, than in monolayer cultures, and Notch1 is highly correlated with the stemness marker among GBM cell lines, suggesting its role in glioma stem maintenance." (PMID 36359750, 2022). "Linc-OIP5 overexpression enhances glioma tumorigenesis through Notch activation, upregulating JAG1, Notch-1 and Hes1 expressions." (PMID 36229883, 2022). "The use of GSIs for cancers is primarily based on the premise that GSIs act by inhibiting the cleavage of γ-secretase, which result in blocking NOTCH1 signaling; modulation of the NOTCH pathway increases glioma cell sensitivity to temozolomide." (PMID 36556190, 2022). "In support of these observations in human brain tumor subtypes, simultaneous genetic inactivation of Notch1 and Notch2 or Rbpj accelerates the growth of PDGF-driven gliomas in mice." (PMID 36358826, 2022). "The interaction of lncRNA FOXD2‐AS1 and TAF‐1 with NOTCH1 was found based on the LncMAP database, and TAF‐1 was initially predicted to be highly expressed in glioma according to the GEPIA website." (PMID 35419917, 2022). "The levels of proteins and mRNA in Notch1, Dll1, Notch4, Dll4, Hey1, Jagged1, CBF1, Hey2, and Hes1 in glioma cells are higher expression than those in healthy brain cells." (PMID 35935338, 2022). "Moreover, the EGFR and MUC16 mutations were also significantly enriched in cases within high‐risk group, while mutations in CIC, NOTCH1, ATRX, and CDH12 occurred more frequently in the low‐risk group, these characteristics are consistent with the update WHO CNS5 classification of glioma." (PMID 35985661, 2022). "This hypothesis is supported by an in vivo CRISPR screen that identified Notch1 among potential tumor suppressors in glioma, and is further in line with the occurrence of NOTCH1, NOTCH2, and RBPJ inactivating mutations and/or reduced Notch signaling activity in human glioma subtypes." (PMID 36358826, 2022). "A potential link between CRYAB, NOTCH1, and BMP pathways is also supported by diffuse low-grade glioma RNA profiles in the TCGA database, showing a significant correlation between CRYAB, BMP2, and HEY2 expression." (PMID 33925547, 2021). "The cross-talk between Notch1 signaling and CXCL12/CXCR4 system contributes to the progression and recurrence of GBM by promoting the self-renewal and invasion of glioma stem cells." (PMID 33552592, 2021). "KMT2A has an epigenetic regulation role on NOTCH1 and NOTCH3, and this mechanism is essential for inhibiting glioma proliferation." (PMID 33711952, 2021). "As NOTCH1 expression is inhibited by this miRNA, high levels of circ-NFIX in glioma cells triggers the upregulation of NOTCH1 and, in this case, the progression of the disease." (PMID 34205978, 2021).
glioma (continued). "Our findings identify NOTCH1 as a central switch between the PVN and network niche in glioma, and demonstrate robust cross-compensation when only one niche is targeted." (PMID 33579922, 2021). "We used primary cultures and a new cell line to explore the influence of NOTCH1 activation and BMP treatment on the IDH1-mutant glioma cell phenotype." (PMID 33925547, 2021). "In a similar experiment, glioma stem cell survival was significantly reduced in vitro after combined RT and a GSI (DAPT or L685.458) and in vivo after combining RT and Notch1/2 shRNA knockdown, as compared to individual treatments." (PMID 34680255, 2021). "As supported by our data above, Notch1 acts downstream to TRPM7 and contribute to the malignancy of glioma." (PMID 33381038, 2020). "TRPM7 is responsible for sustained Notch1 signaling activation, enhanced expression of GSC markers CD133 and ALDH1, and regulation of glioma stemness, which contributes to malignant glioma cell growth and invasion." (PMID 33381038, 2020). "Consistently, external expression of the active intracellular portion of NOTCH1 and NOTCH2 has a protective effect on glioma CSCs, while knock-out of these receptors increase radioresistance." (PMID 32796631, 2020). "As expected, TRPM7 and Notch1 are highly correlated with the GSC markers CD133 and ALDH1 in GSC spheres compared to that in the glioma monolayer cells." (PMID 33381038, 2020). "In summary, TRPM7 is responsible for sustained Notch1 signaling activation, enhanced expression of GSC markers, and regulation of glioma stemness, all of which contribute to malignant glioma cell growth and invasion." (PMID 33381038, 2020). "We compared the expression of the interest pathway molecules in the cell lines and found that the expression of Notch1 signaling genes and CXCR4 was significantly higher in glioma stem like cells and neurospheres than in conventional cell lines." (PMID 31382985, 2019). "Accordingly, inhibition of Notch1 increased the radiosensitivity of TALL-1 T-cell acute lymphoblastic leukaemia cells in vitro and inhibition of Hh signaling in U87 glioma cells increased their radiosensitivity." (PMID 30871073, 2019). "Then, we retrieved data (NCBI GEO dataset: GSE23806) on the expression of Notch1 signaling molecular and CXCR4 in 36 conventional cell lines, 27 glioma stem like cell lines and 17 glioblastoma derived neurospheres." (PMID 31382985, 2019). "Next, we demonstrated that transcript levels of NOTCH pathway members NOTCH1, NOTCH4, DLL1 and HES-1, which carry METTL3-dependent m6A peaks, were downregulated in METTL3-silenced glioma cells." (PMID 30781903, 2019). "In summary, our findings reveal that Notch-1 and OPN are overexpressed in the intermediate (II) and advanced (III) stages of ENU-gliomas." (PMID 30140373, 2018). "Notch-1 and VEGF are overexpressed in ENU-glioma intermediate stage (II), corresponding to angiogenesis switch; in parallel, there is a significant increase in size and density of SAs." (PMID 30140373, 2018). "Recently, several genes have been reported to be prognostic factors in gliomas, such as IDH1, FGFR3, Notch1." (PMID 30524204, 2018). "Our targeted ablation of Notch1 leading to reduced GBM growth and enhanced radiosensitivity offers further evidence of a role of Notch1 in glioma pathogenesis and in cellular response to irradiation damages." (PMID 29152141, 2017). "ShRNA targeting Notch ligand Delta-like 1 (DLL1) decreased CD133 and Nestin expression, and impaired the self-renewal ability of CD133+ U87-MG and U251-MG glioma cells, indicating DLL1/Notch1 signaling promoted stem cell phenotype maintenance." (PMID 28380416, 2017).
glioma (continued). "Consistent with the result of miR-129 overexpression and Notch-1 inhibition, E2F7 also increased Beclin-1 protein levels and induced autophagy in U87 and U251 glioma cells." (PMID 26824182, 2016). "GANT61 sensitizes glioma cells to TMZ treatment by enhancing DNA damage effect, decreasing MGMT expression and the Notch1 pathway." (PMID 27894350, 2016). "To address if the NOTCH pathway was active in our glioma cell lines, we analyzed the gene expression profile of NOTCH receptors (NOTCH1-4), ligands (DLL 1,3,4 JAG 1,2) and target (HES1, HEY1,2) genes." (PMID 27183910, 2016). "Glioma cells treated with TMZ exhibited significant increases in MGMT, Notch1 and Hes1 mRNA, and protein levels." (PMID 27894350, 2016). "Seventeen genes represent active Notch signaling components, including NOTCH1, NOTCH3, HES1, MAML1, DLL-3, and JAG2, which are enriched in the proneural subtype of glioma stem cells." (PMID 26599017, 2015). "For example, the expression levels of Notch1 and GFAP were high in low-grade glioma and differentiated glioma cells but were low in high-grade glioblastoma cells and GSC spheres." (PMID 26563263, 2015). "Reduced levels of miR-34a were also observed in human gliomas, which correlated with increased expression of the target oncogenes c-Met, Notch-1/2 and cyclin-dependent kinase 6 (CDK6) in glioma and stem cells." (PMID 24275848, 2013). "Prior reports have shown that miR-34a is downregulated in GBM compared to normal brain, and that it inhibits cell proliferation, survival, and invasion in adherent glioma cell lines by targeting MET, NOTCH1, NOTCH2, and CDK6." (PMID 22479456, 2012). "To clarify whether NOTCH1 is involved in PDGF‐D‐mediated EMT in glioma cells, we activated NOTCH1 in the PDGF‐DKD LN18 cells with Dll4 and inhibited NOTCH1 cleavage in the PDGF‐DOE U87 cells using DAPT." (PMID 40530904, 2025). "Recent evidence suggests that β-1,4GalT-V may glycosylate Notch-1 and, thus, regulate a VEGF-independent angiogenic pathway, promoting glioma-like stem cell differentiation into endothelial cells, thus contributing to angiogenesis." (PMID 40869407, 2025). "Changes in NOTCH1 and SOX2 were present in all glioma types." (PMID 40679044, 2025). "NOTCH1, SOX2, TJP1/ZO1, ZEB1, and ZEB2 have higher expression in lower-grade glioma vs GBM." (PMID 40679044, 2025). "All in all, we concluded that knockout of the Notch1 gene enhances the glioma therapeutic effectiveness of TMZ and further confirmed that the Notch1 gene is a key molecule in the reversal of TMZ resistance in glioma." (PMID 39544152, 2024). "In glioma, BRD4 (and not BRD2 or BRD4) sustained the self-renewal of glioma-initiating cells by modulating the Notch1 signaling pathway, and significant inhibition of BRD4 resulted in the loss of stem cell-like properties of glioma cells." (PMID 36674511, 2023). "Considering that NOTCH1 is a marker of glioma stem cells, it is suggested that non-responders harbor more glioma stem cells than responders." (PMID 36694264, 2023). "For instance, NOTCH1 signaling suppresses MIR139 expression via the transcriptional repressor HES1, which binds to the E-box site at position +644 bp in the PDE2A gene in glioma cells." (PMID 35269391, 2022).
glioma (continued). "They explored the ability of glioma stem cell (GSC) exosomes to reprogram non-GSC glioma cell lines through the release of Notch-1, known to be important in the maintenance of the cancer-stem-like phenotype and upregulated in glioma stem cells (GSCs)." (PMID 34638913, 2021). "In human cancers in general as well specifically in gliomas, both Notch1 and β-catenin are connected with the process of EMT and therefore, we next evaluated Notch1 and β-catenin in our study." (PMID 34485294, 2021). "PI3k/Akt signaling regulates angiogenesis by affecting expressions of VEGF, HIF-1α, and MMP9.Activation of PI3k by Notch1 also stimulates the signaling pathways of MMP9, β-catenin, and NF-κB, which increases the migratory, invasiveness, and angiogenic properties of glioma cells." (PMID 36643842, 2021). "Finally, targeting Notch1 effectively suppressed TRPM7-induced growth and proliferation of glioma cells through cell G1/S arrest and apoptotic induction." (PMID 33381038, 2020). "Notch1 activation was shown to promote tumor growth and drive acquired resistance to mitogen-activated protein kinase (MAPK) inhibitors in melanoma, as well as TMZ resistance in melanoma and glioma." (PMID 32899791, 2020). "Given the importance of Notch1 in pathway regulation and in the biology of glioma, out of the top genes we chose Notch1 and tested a novel Notch1-targeting clinical drug candidate on stem cell models of glioblastoma." (PMID 33004830, 2020). "Overexpression of Notch-1 and its ligands, Delta-Like-1 and Jagged-1, is critical for glioma cell survival and proliferation, and activation of Notch via expression of NICD1 promotes growth and neurosphere formation of the SHG-44 glioma cell line." (PMID 33014056, 2020). "Based on our data that NAKP controlled the expression and secretion of SDF-1 and M-CSF via Notch1, it could be concluded NKAP was involved in regulation of the tumor immune microenvironment of gliomas." (PMID 31277684, 2019). "In contrast to a higher immunostaining of Notch1 and SDF-1 in the gliomas derived from the cells transduced with scrambled control shRNA, the gliomas depleted of NKAP displayed much lower levels of these two factors, evidently suggesting a regulatory role of NKAP in Notch1 signaling." (PMID 31277684, 2019). "Furthermore, Notch1, Hes1 and CXCR4 expressing cells colocalized with or adjacent to the Nestin expressing glioma cells." (PMID 31382985, 2019). "Notch1 activation under hypoxic conditions also induces the expression of transient receptor TRCP6, which has emerged as a critical player in Glioblastoma aggressiveness, promoting NFAT activity, a crucial factor for glioma proliferation." (PMID 30832246, 2019). "To further investigate the mechanism of miR-139-5p on glioma suppression, we sought to determine whether the anti-EMT effects of miR-139-5p are mediated by Notch1." (PMID 30170559, 2018). "In this study, we validated that Notch1 and NF-κB(p65) are highly expressed in the classical and proneural subtypes of GBM using the data set from The Cancer Genome Atlas (TCGA) and the Chinese Glioma Genome Atlas (CGGA)." (PMID 29410396, 2018). "Given that Notch1 is highly expressed in glioma and a crucial regulator of epithelial-mesenchymal-transition (EMT), we subsequently investigated its biological importance on the tumourigenic property of glioma cells, including metastasis and invasion." (PMID 30170559, 2018). "Glioma cells, especially U87 and LN229 cells, expressed more Notch1 compared with Olig." (PMID 30170559, 2018). "Notch-1 and osteopontin (OPN) mediate angiogenesis and glioma stem-like cell (GSLC) maintenance." (PMID 30140373, 2018). "Knocking-down NOTCH1 inhibited cell proliferation of ICC cells and glioma cells." (PMID 28388563, 2017). "NOTCH1 expression is higher in grade II and III gliomas but lower in more malignant gliomas." (PMID 28968975, 2017).